CRKL (CRK like proto-oncogene, adaptor protein)
Diseases named in the same sentence as CRKL in open-access papers (continued):
Sharing a sentence is not in itself a finding about the gene and the disease.
gastric cancer (continued). "As expected, the percentage of gastric cancer cells with CRKL amplification was significantly higher in the high expression group (9.1%; 8/88 cases) than in the low expression group (2.2%; 6/272 cases) (P = 0.028, chi-square test)." (PMID 22591714, 2012). "An increase in the copy number was confirmed in MKN74 gastric cancer cells with CRKL amplification using a FISH analysis, and a high CRKL expression level was also observed in these cells." (PMID 22591714, 2012). "Our genome-wide SNP microarray analysis successfully revealed, for the first time, that the CRKL gene is highly amplified in a subset of gastric cancers." (PMID 22591714, 2012). "Next, we investigated the expression status of CRKL protein in primary gastric cancer using an immunohistochemical analysis with anti-CRKL monoclonal antibody (Y243)." (PMID 22591714, 2012). "Through a genome-wide SNP microarray analysis performed in this study, the CRKL gene was identified as a highly amplified gene in gastric cancer." (PMID 22591714, 2012). "Since the AGS gastric cancer cell line had lower CRKL mRNA and CRKL protein expression levels than MKN74 cells and had a normal CRKL genomic copy number, these cells were treated with BMS354825." (PMID 22591714, 2012). "The CRKL copy number was also examined in 360 primary gastric cancers using a FISH analysis, and CRKL amplification was found to be associated with CRKL overexpression." (PMID 22591714, 2012). "To explore the functional significance of CRKL amplification in gastric cancer, we attempted to examine the effect of overexpressed CRKL on gastric cell proliferation." (PMID 22591714, 2012). "We also investigated responsiveness of a gastric cancer cell line containing CRKL amplification to a kinase inhibitor, BMS354825, and a CRKL-targeting peptide." (PMID 22591714, 2012). "In addition, miR-126 was identified as a tumor suppressor in gastric cancer and as an inhibitor of V-crk avian sarcoma virus CT10 oncogene homolog-like (CRKL)thanks to its targeting of the 3’ UTR region of CRKL mRNA or VEGF-A mRNA." (PMID 28536606, 2016). "In the present study, we modulated the expression of CRKL in SGC-7901 cells, and observed that the depletion of CRKL in gastric cancer SGC-7901 cells was companied with a down-regulation of SLC7A5 at both mRNA stage and protein stage, which suggests SLC7A5 as a downstream gene of CRKL." (PMID 27846244, 2016). "Accordingly, we conclude that SLC7A5 functions as a promoter in gastric cancer metastasis, and CRKL could be one of its regulators modulating the expression of SLC7A5 and consequentially affect the metastatic feature of SGC-7901 cells." (PMID 27846244, 2016). "We hypothesized that CRKL might play an important role in gastric carcinogenesis and investigated whether CRKL expression and the function of CRKL protein affect the regulation of cell proliferation in gastric cancer." (PMID 22591714, 2012). "Our results suggest that the CRKL protein may be a target of BMS354825-mediated therapy for a subset of gastric cancers." (PMID 22591714, 2012). "Furthermore, we conclude that CRKL protein has the ability to regulate gastric cell proliferation and has the potential to serve as a molecular therapy target for gastric cancer." (PMID 22591714, 2012). "Thus, CRKL overexpression arising from genomic amplification likely contributes to the aggressiveness of gastric cancer." (PMID 22591714, 2012). "We further investigated whether the levels of CRKL expression is associated with clinicopathological features in primary gastric cancer patients, the high CRKL expression was observed significantly more often in male and differentiated-type gastric cancer." (PMID 22591714, 2012). "Furthermore, our results suggested that CRKL protein has the ability to regulate gastric cell proliferation and has the potential to serve as a molecular therapy target for gastric cancer." (PMID 22591714, 2012).
gastric cancer (continued). "Thus, SLC7A5 functions as a promoter in gastric cancer metastasis, and CRKL could be one of its regulators modulating its expression and consequentially affects the metastatic feature of SGC-7901 cells." (PMID 27846244, 2016). "To examine whether CRKL overexpression is associated with CRKL amplification in gastric cancer, we performed a FISH analysis for the CRKL gene in the 360 primary gastric cancers and compared the prevalence of CRKL amplification between the low expression group and the high expression group." (PMID 22591714, 2012). "CRKL is known to promote metastasis and the EMT process in cancers such as hepatocellular carcinoma, cervical cancer, and gastric cancer and correlates with a poor prognosis." (PMID 37894400, 2023). "CrkL knockdown also resulted in a decrease in CCL20-induced migration and invasion of gastric cancer cells." (PMID 33801580, 2021). "CrkL knockdown inhibited CCL20/CCR6-induced EMT marker expression and ERK phosphorylation in gastric cancer cells by decreasing expression of N-cadherin, vimentin, and MMP2." (PMID 33801580, 2021). "The knockdown of CrkL abrogates the CCL20-induced pERK, vimentin, N-cadherin, and MMP2 expression with decreased migration and invasion of gastric cancer cells." (PMID 32707869, 2020). "By studying the gastric cancer cell lines and clinical pathological specimens, we found that the expression of SLC7A5 was significantly correlated to CRKL." (PMID 27846244, 2016). "In summary, in this study, both CRKL and SLC7A5 were over-expressed in gastric cancer cell lines and tissues." (PMID 27846244, 2016). "The findings in this study indicate a regulation relationship between CRKL and SLC7A5, and provide useful evidence for gastric cancer therapeutic strategies." (PMID 27846244, 2016). "Results above, combining with what we observed in tumor cells and tissues, strongly illustrate a positive correlation between CRKL and SLC7A5 in gastric cancer cells." (PMID 27846244, 2016). "The findings here indicate a regulating relationship between CRKL and SLC7A5, and provide further evidence to advance new targets for gastric cancer therapeutic treatment." (PMID 27846244, 2016). "An extremely high CRKL copy number was confirmed in the MKN74 gastric cancer cell line using fluorescence in situ hybridization (FISH), and a high level of CRKL expression was also observed in the cells." (PMID 22591714, 2012). "Furthermore, elevated expression of Crk or CrkL correlated with the poor prognosis in GBM, lung cancer, gastric cancer, ovarian cancer, oral squamous cell carcinoma, pancreatic cancer, and colorectal cancer." (PMID 33561443, 2021). "To further characterize the role of CRKL in the BMS354825-induced suppression of MKN74 cell viability, we examined the effect of BMS354825 on gastric cancer cells without CRKL amplification." (PMID 22591714, 2012). "It was shown to be downregulated and might function as a tumor suppressor by targeting Myc, FSCN1 in gastric cancer, ZEB1 in oral squamous cell carcinoma, CRKL in hepatocellular carcinoma, TLN1 in nasopharyngeal carcinoma, AKT1 in melanoma, or BCL2 and SP1 in esophageal carcinomas." (PMID 33414893, 2020). "On the other hand, CrkL played a crucial role in mediating the EMT induced by the CCL20/CCR6 axis through the Akt signaling pathway, rather than the Erk1/2 pathway during gastric cancer development." (PMID 40362257, 2025). "A similar analysis using cBioPortal of a smaller subset for lung, breast, and gastric cancer patients combined did not exhibit any apparent difference in overall survival among the patients with amplification of CRK and CRKL transcripts (data not shown)." (PMID 33801580, 2021).
DiGeorge syndrome (13 papers, 2014 to 2024). "CD34 is furthermore intracellularly coupled to CRKL, which has been associated with congenital kidney anomalies in DiGeorge Syndrome, including microcystic tubules and glomeruli." (PMID 34301992, 2021). "TBX1 and CRKL haploinsufficiency is thought to cause the cardiac phenotype of the 22q11.2 deletion syndrome." (PMID 24998776, 2014). "Moreover, the heterozygous inactive mutation in CrkL in humans has been reported to cause congenital kidney anomalies of DiGeorge syndrome." (PMID 33801580, 2021). "SROs with candidate genes were found in the established risk loci for other syndromes known to be associated with hypospadias, such as Silver–Russell Syndrome (PSMD13); 13q Deletion Syndrome (COL4A1); and 22q Deletion/Duplication Syndromes, which includes DiGeorge Syndrome (CRKL)." (PMID 35457073, 2022). "The expression level of the CRKL (MIM: 602007), a potential modifier of cardiac development in 22q11.2 deletion syndrome and a possible target of noncoding putative regulatory variants, was unaffected." (PMID 38608674, 2024). "Genes that may influence the phenotype may be similar to genes involved in the same deleted region in DiGeorge syndrome (DGS; OMIM 188400) and velocardiofacial syndrome (VCFS; OMIM 192430) (mainly TBX1, HIRA, CRKL)." (PMID 36226175, 2022). "The CRKL gene has previously been recognized as an important factor during normal maturation of human kidneys, as well as in the appearance of DiGeorge syndrome due to the lack of differentiation and migration of kidney cells." (PMID 34502088, 2021). "Among them, CRKL, TBX1, TXNRD2, GP1BB were known to be involved in DiGeorge syndrome." (PMID 26742958, 2016).
lung carcinoma (13 papers, 2016 to 2025). "Also, the HBE and H1299 cell lines of lung carcinomas showed a notable rise in colony formation associated with CrkL overexpression, compared to the controls." (PMID 40362257, 2025). "Other genes from this pathway that we found differentially expressed in our experiments are CBLC that was reported as associated with lung cancer progression and CRKL which promotes tumorigenesis, cancer cell survival, and gefitinib therapy resistance in non-small cell lung cancer." (PMID 35290621, 2022). "When this list was limited to the genes associated with poor patient prognosis in lung cancer, only 29 genes came up as statistically significant, with CRKL as the gene with the most reasonable relationship to the observed phenotype of cytoskeletal re-organization and FAK signaling." (PMID 26728244, 2016). "In lung carcinomas, the expression of the CrkL protein was significantly elevated relative to that in adjacent normal lung tissue." (PMID 40362257, 2025). "The overexpression of CrkL in the HBE and H1299 cell lines associated with lung carcinomas stimulated cell proliferation by advancing cell cycle progression." (PMID 40362257, 2025). "In particular, both Crk and CrkL have been reported to be overexpressed in ovarian, breast, gastric, and lung cancer tissues." (PMID 33801580, 2021). "Consistent with our data, CRKL was recently identified as a novel lung cancer driver, found on a common focal amplification." (PMID 26758680, 2016). "In lung cancer, overexpression of CRKL facilitated cell invasion via ERK-MMP9 pathway." (PMID 38289488, 2024). "Ovarian, breast, gastric, and lung cancers exhibited elevated expression of both Crk and CrkL." (PMID 33801580, 2021). "Here we have shown that the adaptor molecule, CRKL, is a direct miR-200bc target, functionally affecting experimental migration, invasion and metastasis of lung cancer cells and clinically prognostic of outcome in multiple tumor types from analysis of TCGA datasets." (PMID 26728244, 2016). "For example, hsa-miR-1827 has been reported to be downregulated in highly invasive lung cancer sub-cell lines, and the overexpression of miR-1827 inhibits lung cancer cell migration via targeting RBX1 and CRKL." (PMID 36111773, 2023). "Efficient knockdown of ABL1 and ABL2 proteins and decreased phosphorylation of the ABL substrate p-CrkL was observed in both PC9 and HCC827 lung cancer cells." (PMID 33119681, 2020). "Immunoblot analysis of sorted lung cancer cells from MSC co-cultures revealed activation of ABL kinases as measured by ABL tyrosine (Y245) phosphorylation and phosphorylation of ABL downstream targets STAT3 (Y705) and CrkL (Y207)." (PMID 33119681, 2020).
chronic myeloid leukemia (12 papers, 2010 to 2025). "In the present study, CRKL upregulation was negatively correlated with miR‐429 downregulation in both chronic myeloid leukaemia (CML) patient and CR patient samples." (PMID 38683131, 2024). "In chronic myeloid leukemia, CRKL is a crucial BCR/ABL substrate that can bind to both c-ABL and BCR/ABL." (PMID 37894400, 2023). "CRKL has a role in platelet aggregation through inducing tyrosine phosphorylated via thrombopoietin in both chronic myeloid leukemia patients’ and upregulated in myocardial infraction patients’ platelets." (PMID 27336623, 2016). "CRKL is well known as a surrogate substrate of BCR-ABL kinase in chronic myeloid leukemia and acute lymphoblastic leukemia, and intensive studies of CRKL in Philadelphia chromosome-positive leukemia have been performed." (PMID 22591714, 2012). "In cellular assays, it inhibited the proliferation of BCR-ABL driven chronic myelogenous leukemia (BaF3) cells as judged by the inhibition of CRKL (v-crk sarcoma virus CT10 oncogene homolog (avian)-like) phosphorylation." (PMID 22350019, 2012). "Via the pathway analysis, we also found that CRKL is associated with a number of pathways, for instance, the MAPK signaling pathway, chronic myeloid leukemia and the regulation of the actin cytoskeleton pathways." (PMID 20419126, 2010). "Overall, in various types of cancer, such as breast, prostate, ovarian, lung, colorectal, pancreatic, and hepatocellular carcinoma, as well as in glioma, melanoma, anaplastic large cell lymphoma, and chronic myelogenous leukemia, there has been an increase in the expression of p130Cas and Crk/CrkL." (PMID 40362257, 2025).
hepatocellular carcinoma (12 papers, 2018 to 2025). A malignant tumor that arises from hepatocytes. "CrkL has been identified as a factor associated with the malignant behavior of Hca-P, a murine hepatocellular carcinoma cell line with a lymph node metastatic rate of 25%." (PMID 40362257, 2025). "Analyses of gene profiling have revealed that CrkL was a likely downstream target of the miR–215–PCAT-1 axis in hepatocellular carcinoma." (PMID 40362257, 2025). "A previous study has reported that overexpression and interference of CRKL strikingly facilitated and curbed migration and invasion abilities of hepatocellular carcinoma HepG2 cells." (PMID 38289488, 2024). "For instance, in hepatocellular carcinoma, miR-429 targets CRKL, inhibiting tumor migration and invasion via the Raf/MEK/ERK signaling pathway and epithelial-mesenchymal transition." (PMID 38914806, 2024). "CrkL knockdown also inhibited in vivo tumor growth in head and neck squamous cell carcinoma, rhabdomyosarcoma, hepatocellular carcinoma, and colorectal cancer cells." (PMID 33801580, 2021). "In addition, colony formation in hepatocellular carcinoma cells reinforced the oncogenic characteristics attributed to CrkL, and the elevated levels of CrkL counteracted the tumor-suppressive functions of miR-215." (PMID 40362257, 2025). "Additionally, miR-429 was suggested as a tumor suppressor in hepatocellular carcinoma by targeting CRKL via inhibiting the Raf/MEK/ERK pathway and the epithelial-mesenchymal transition, which leads to a decrease in tumor migration and invasion." (PMID 38002073, 2023). "By interacting with AFAP1-AS1, CRKL encourages the growth and EMT of hepatocellular carcinoma cells." (PMID 37894400, 2023).
cervical cancer (9 papers, 2018 to 2025). A primary or metastatic malignant neoplasm involving the cervix. "For example, the effect of CRKL on alternative splicing may be significantly associated with tumourigenesis in cervical cancer." (PMID 33976726, 2021). "The expression levels of ZEB1 and CrkL exhibited an inverse correlation with miR-429 levels in cervical cancer cell lines." (PMID 40362257, 2025). "The overexpression of CrkL significantly promoted cell proliferation within CaSki cervical carcinoma cell lines." (PMID 40362257, 2025). "CrkL knockdown also inhibited cell motility in head and neck squamous cell carcinoma and migration and invasion of cervical cancer cells." (PMID 33801580, 2021). "CrkL knockdown also inhibited colony formation of glioma and cervical cancer cell lines on soft agar." (PMID 33801580, 2021). "Whereas CrkL overexpression inhibited migration and invasion of murine hepatocarcinoma cells, CrkL overexpression promoted invasion of cervical carcinoma cells." (PMID 33801580, 2021). "To uncover the CRKL-regulated alternative splicing events (ASEs) in cervical cancer samples, we selected 40 cancer samples with 20 showing high CRKL expression and 20 showing low." (PMID 31133010, 2019). "To this end, we knocked down CRKL by shRNA in HeLa cells (sequencing information of shRNA was shown in Methods), derived from a cervical cancer patient, and analyzed the cell proliferation rate." (PMID 31133010, 2019). "We then sought to study how the CRKL-regulated ASEs revealed by RNA-seq in HeLa cells were also regulated by CRKL expression in cervical cancer samples." (PMID 31133010, 2019). "We showed that CRKL-regulated ASEs revealed by computational analysis using ABLas software in HeLa cell were highly validated by RT-qPCR, and also validated by cervical cancer clinical samples." (PMID 31133010, 2019). "It is interesting to find that a number of GO biological pathways enriched by CRKL-regulated alternative splicing in HeLa cell were similar to those in cervical cancer samples." (PMID 31133010, 2019). "We further explored the relationship between CRKL expression and progression stages of most cervical cancer, with the stages containing at least 5 samples were selected." (PMID 31133010, 2019). "These functional pathways that CRKL-regulated alternative splicing events enriched in are similar as those in cervical cancer samples." (PMID 31133010, 2019). "Also, the expression levels of CrkL were predominantly increased in samples of stage 1 cervical cancer, and the silencing of CrkL resulted in a decrease in cell proliferation." (PMID 40362257, 2025). "Interestingly, CrkL overexpression led to increased chemoresistance to cisplatin treatment in cervical carcinoma and endometrial carcinoma cells." (PMID 33801580, 2021). "The expression of CRKL was mostly up-regulated in stage I cervical cancer samples." (PMID 31133010, 2019). "We analyzed the expression level of CRKL in 305 cervical cancer tissue samples available in TCGA database, and then selected two groups of cancer samples with CRKL differentially expressed to analyzed potential CRKL-regulated alternative splicing events (ASEs)." (PMID 31133010, 2019). "Inspired by previous studies on the overexpression of CRKL in a small number of cervical cancer samples, we downloaded RNA-seq expression data for all samples available for cervical cancer in TCGA (The Cancer Genome Atlas) database, which included 305 cervical tumor and 3 normal samples." (PMID 31133010, 2019). "Moreover, significantly more CRKL-regulated alternative splicing events detected in HeLa cells were positively than those negatively correlated with the CRKL expression level in cervical cancers." (PMID 31133010, 2019). "This indicated that the effect of CRKL on alternative splicing might be significantly related to tumorigenesis in cervical cancer." (PMID 31133010, 2019).